CD4 (CD4 molecule)
Diseases named in the same sentence as CD4 in open-access papers (continued):
Sharing a sentence is not in itself a finding about the gene and the disease.
infection (continued). "We found that antigen-experienced CD4+ T cells expanded and were retained at high numbers in persistently infected mice, whereas control mice experienced expansion of these cells followed by contraction as the infection was cleared." (PMID 27583554, 2016). "Utilizing the LPAC model, we previously demonstrated that commensal E. coli activated bacteria-reactive intestinal T cells, augmented HIV-1 replication and infection of CD4 T cells and increased the death of productively infected cells through increased apoptosis in vitro." (PMID 26762145, 2016). "With the aim of measuring the frequency and level of activation of CD4+ T cells in vivo during infection, mice were injected i.p. with Brefeldin A solution and CD4+ T cells were directly isolated from the spleen 96 h post-primary infection." (PMID 27905502, 2016). "However, by week 3 post-infection, there was a substantial reduction in CD4+ T cells expressing these Tfh cell markers in Icos−/− mice, and the remaining Tfh cells were unable to form PD-1++CXCR5++ GC Tfh cells." (PMID 27559335, 2016). "Notably, anti-Tat Abs are uncommon in natural infection and, when present, correlate with the asymptomatic state, higher CD4+ T-cell number, lower viral load, and reduced disease progression." (PMID 27277839, 2016). "Together this may provide a favourable environment for ongoing infection of resting CD4+ T-cells, even in the presence of very low levels of HIV that could persist in HIV infected subjects on ART." (PMID 27383184, 2016). "Thus, the antigen-driven expansion of CD4+ Th9 cells in Ss infection is reversible (for the most part) following treatment of infection." (PMID 26730582, 2016). "In order to explain the observed dynamics of TRECs and naive T-cell numbers in the CD4+ T-cell pool, on the other hand, the turnover of naive T cells during the acute phase of infection should have been higher than we observed using deuterium labeling during chronic infection." (PMID 27010200, 2016). "CD4+ T cells are known to secrete a variety of proinflammatory cytokines and chemokines that are capable of recruiting and activating other immune cells at the site of infection." (PMID 27600502, 2016). "This developmental link between CD4+Foxp3+ Tregs and IL-17+CD4+ Th17 cells has led to speculation that these T cell subsets exist in equilibrium during inflammation and infection." (PMID 27439902, 2016). "We elicited LCMV primed T cells in congenic wild type mice, purified CD4+ T cells on day 8 post-infection at the peak of T cell expansion, and adoptively transferred the cells into naïve Myd88-/-, IL-1R-/-, TLR2, 3, 4, 7, 9-/-, TLR3, 7, 9-/- and wild type mice." (PMID 27542117, 2016). "However, studies have shown that both naive and memory CD4+ T cells contain integrated viral DNA, and that direct infection of resting CD4+ T cells in lymphoid tissue results in productive infection." (PMID 26067822, 2015). "In addition, infection with Salmonella led to a significant decline in the proportions of CD4+ and CD8+ T lymphocytes in stained tissue sections of spleens analyzed by IFM and in splenic cell suspensions analyzed by flow cytometry." (PMID 26068006, 2015). "Like others, while some early analyses herein showed HIV-infection and lower CD4+ T-cell counts showed higher risk of HPV16/18 infection, the association was not statistically significant in the final model." (PMID 25794147, 2015). "Naïve control mice depleted from CD4+ or CD8+ also succumbed infection." (PMID 26650916, 2015). "CV-B4 infection of the thymus leads to increased secretion of diverse cytokines synthesized in TECs, to a severe depletion of double positive CD4+CD8+ thymocytes, and to marked up-regulation of MHC class I molecules expressed by TECs and double positive thymic T cells." (PMID 26175734, 2015). "The induction of CD4+ Th1 cells response for parasite antigens is crucial in controlling infection." (PMID 26367128, 2015).
infection (continued). "Interestingly, on day 3 post-infection, a greater percentage of splenic CD4+ T cells in the FeD mice had an activated phenotype and expressed CXCR3." (PMID 25768944, 2015). "While CD4+ T cells are sufficient to drive increased IEC proliferation, it was unclear whether the reduced CD4+ T cell numbers found in infected Retnlb-/- mice reflected a defect in their priming, or in their recruitment to the site of infection." (PMID 26285214, 2015). "Indeed, depletion of CD4+ T cells in GITRL tg mice abrogated the early increase in CD8+ T cell expansion during the first week of the infection and induced a crash of both the total CD8+ T cell pool and the LCMV-specific CD8+ T cells at day 15 p.i.." (PMID 25738498, 2015). "In that work, mice given IL-12 showed a significant augment in IFN-γ production at the beginning of infection and reduction of Th1/Th2-related cytokines at the late stage of infection, similarly to what was observed in the present study for Rag1-/- mice injected with CD4+Foxp3- T cells." (PMID 26512987, 2015). "Hence, we amplified the entire protein-coding region of the viral DNA directly from peripheral blood mononuclear cells (PBMCs) of 11 treatment-naive patients with known infection, viral load, and CD4 count histories." (PMID 26375597, 2015). "Within this susceptible population, single and double infection could be following the expected Poisson distribution but the large proportion of cells resistant to the virus gives the appearance of enhanced double infection in the total CD4+ T cell population." (PMID 26559763, 2015). "The ability to recognize multiple variants of a class I epitope may be the most important during the acute phase of infection before effective CD4+ and CD8+ T cell immunity is lost." (PMID 25537849, 2015). "However, one day after infection, the proportion of IL-10 producing cells was equally split between CD4+ T cells and F4/80+MHC-IIhigh macrophages." (PMID 25974019, 2015). "Du point de vue maternel, les informations recueillies ont été: l’âge, la parité, le stade clinique selon l'OMS, la présence d'infections opportunistes, le nombre de lymphocytes CD4, le moment de dépistage, la période de mise sous TARV et le TARV reçu (classé en mono-, bi- et trithérapie)." (PMID 26600917, 2015). "Resting CD4 T cells express Gag protein after direct infection in vitro." (PMID 26537682, 2015). "Both immature and mature DCs are capable of eliciting trans-infection of CD4+ T-cells." (PMID 25809903, 2015). "While many teams all over the world were trying unsuccessfully to identify such CD4 cofactor(s) enabling productive infection by HIV, scientist working in the field of chemokines were making tremendous progress identifying new chemokines and receptors and elucidating their biological roles." (PMID 26097474, 2015). "Interestingly, residues 82–85 in C protein have also been identified as a CD4+ T-cell epitope and C-R82K substitution detected in an individual DF infection of the present study resides within this motif." (PMID 25811657, 2015). "Since 4-1BBL-/- mice show normal primary expansion of CD8+ T cells against influenza virus but decreased T cell numbers 3–5 weeks after the infection, it is possible that 4-1BBL on CD4+ T cells is also involved in providing the help for memory CD8+ T cell generation." (PMID 25962156, 2015). "In addition, HIV-1 Nef intersects the macrophage CD40L signaling pathway and promotes the resting CD4+ T cell infection by inducing soluble CD23 and soluble ICAM." (PMID 25835530, 2015). "Furthermore, it is recognized that GALT is the main region for HIV replication and massive CD4+ T cells depletion in early infection is observed in this compartment." (PMID 26568963, 2015). "How HIV latency is established in activated CD4+ T cells immediately after infection is still unknown, but it may arise from stochastic viral gene expression." (PMID 26067822, 2015). "DCs were also required for CD4+ T cell responses during infection." (PMID 25658925, 2015).
infection (continued). "Independently from preterm birth, low maternal CD4+ cell count at delivery was associated, although not significantly, with an increased risk of infection particularly for the neonatal period." (PMID 26284528, 2015). "By respective gates, Ki-67+CD4+ T cells were separated into naïve CD8α− cells and antigen-experienced CD8α+ cells and, again, absolute numbers were calculated in the time course following infection." (PMID 25971313, 2015). "Tfh cells express CD95 and because CD95L have been shown to be elevated in pathogenic compared to non-pathogenic infections, and are involved in the death of memory CD4 T cells, it cannot be excluded that FasL is directly involved in the death of Tfh cells." (PMID 26640894, 2015). "Interestingly, we found that IFN-γ+CD3+CD4- T cells also increased in MAP27-immunized mice post infection." (PMID 26317210, 2015). "The CD4+ T cell count progressively declines during approximately the eight years post-infection." (PMID 29061947, 2015). "A biological methodology such as the one we used to identify recent infections seems to be more reproducible than declaration or biological indicators such as CD4 T-cell count, seroconversion, p24 antigen assay or frequency of ambiguous nucleotides in sequencing to date the infection." (PMID 26267615, 2015). "Targeted suppression of CD4+ T cell activation, in combination with antiviral therapies may nevertheless offer a useful approach, if used early on in infection." (PMID 25837979, 2015). "We collected the information on CD4 count and viral load in the suspected transmitting partners only after the transmission event was documented, typically one to three months after the estimated date of infection (median of 58 days)." (PMID 26291456, 2015). "However, we also observed reduced but significant losses of CD4+ T cells in tissues with JRCSFNefdd infection." (PMID 26169178, 2015). "Our data therefore suggest that M3R-dependent protection against infection may primarily be a function of altered CD4 T cell responsiveness." (PMID 25629518, 2015). "The infection kinetics in resting CD4+ T cells seem to be slower than in activated cells, since peak infection was not reached until 6 days after infection, while activated cells reached peak infection 4 days after infection." (PMID 26067822, 2015). "Infection with cryptosporidium species and other intestinal parasites among non-HAART patients, as is documented by other studies in Ethiopia and Nigeria, were significantly associated with having CD4 count <350 cells/μL." (PMID 25658626, 2015). "Following the second infection, an increase of Ki-67+CD4+ T cells could be detected in animals #4, #6 and #7." (PMID 25971313, 2015). "We wanted to evaluate whether their predominance was due to the evolution of an enhanced ability of the envelope glycoproteins to mediate infection of CD4+ T-cells." (PMID 25809903, 2015). "Finally, the production of IL-10 in the skin, which derived from a combination of schistosome-specific and commensal microbiota-specific CD4+ T cell responses, contributed towards limiting inflammation and tissue damage following infection." (PMID 25974019, 2015). "Taking into account the rapid clearance of FLUAVsw infections, we hypothesized that highly differentiated CD4+ and CD8β+ T cells with multiple effector functions are involved in protective immune responses." (PMID 25971313, 2015). "The percentages of IFNγR2- and T-bet-expressing CD4+ T cells were increased in both groups on day 7 post-infection compared to day 3 post-infection; however, the percentages of IFNγR2+ and T-bet+ CD4+ T cells were markedly reduced in the FeD mice on day 7 post-infection." (PMID 25768944, 2015). "In fact, the isolated uninfected population of resting CD4+ T cells contained more silently infected cells than the number of latently infected cells that were identified via the mCherry fluorescent marker after the initial infection." (PMID 26067822, 2015).
infection (continued). "We previously showed that directly infected resting CD4+ T cells expressed very low levels of Env, but we had not addressed whether Nef could be expressed in resting cells after direct infection." (PMID 26537682, 2015). "This small multifunctional CD4+ T-cell population has high proliferative potential and may be important for protection against future infection." (PMID 26606759, 2015). "However, HTLV-1 modifies the behavior of CD4+ T cells on infection and alters their cytokine production." (PMID 26712781, 2015). "However, loss of Vpr at the cell surface is at odds with models require endosomal uptake during or after CD4 and co-receptor engagement for fusion, entry and infection." (PMID 25807494, 2015). "BnAbs were thus present during the entire infection process and could act both, before and after CD4 attachment." (PMID 26158270, 2015). "It remains to be seen, in vivo, if productively infected CD4+ T cells can survive long enough to return to a resting state and contribute to the latent pool, or if activated CD4+ T cells that become latently infected immediately after infection are the major contributors." (PMID 26067822, 2015). "Apart from animal #9, an increase of cytokine+CD4+ T cells following the second infection could be detected in animals #6, #7 and #8." (PMID 25971313, 2015). "Consequently, the Gr1intCD11b+ cells that was isolated from the lungs of Mtb-infected mice at 28 days post-infection significantly decreased CD4+ and CD8+ T cell proliferation under DC-T cell co-culture conditions." (PMID 26675186, 2015). "Similarly, infection of mice that contain specific memory CD4 T cells with chronic LCMV leads to rapid and extensive weight loss, widespread inflammation and tissue destruction." (PMID 26441961, 2015). "Though Cda2 contains a dominant CD4+ T cell epitope, cross-reactivity to other closely related cryptococcal proteins likely account for the remaining tetramer binding Th cells generated during infection with cda2Δ." (PMID 25764512, 2015). "However, it has recently become clear that effector CD4+ T cell production of IL-10 plays an important role in limiting host pathology and promoting chronicity of infection." (PMID 26417443, 2015). "Thus, mechanisms other than direct infection are responsible for the depletion of CD4+ T cells in BAL in acute SIV infection." (PMID 25933119, 2015). "Whether IE-1-specific T cells (CD8 or CD4) are of superior importance in control of infection has remained more controversial." (PMID 26635812, 2015). "Although IFN-γ+ CD4 T cells induce immunity to chlamydial infection, they might have detrimental effects on the primary site of infection resulting in collateral damage." (PMID 26029217, 2015). "Interestingly, CCL19 treatment of resting CD4+ T cells produced 0.2% reactivatable provirus from the isolated uninfected cell population, while the initial latent cell population after infection was 0.47%." (PMID 26067822, 2015). "HIV-1 mainly targets human CD4+ T cells that continue to harbor latent proviruses after infection." (PMID 26489856, 2015). "However, in a murine model of infection by C. albicans, mice given both cell subpopulations displayed lower fungal burden compared to those receiving CD4+CD25- T cells only." (PMID 26512987, 2015). "However, the high infection rate of CMV results in a virtually absolute cooccurrence with CD4+CD28− T cells." (PMID 25834833, 2015). "However, eventual resolution of infection is dependent on CD4 T cell-coordinated responses, and higher bacterial loads in M3R−/− mice were associated with reduced IFN-γ from day 18 onwards." (PMID 25629518, 2015). "However, when latently infected memory CD4+ T cells encounter an antigen or are exposed to specific cytokines or chemokines, proviral transcription is activated, leading to productive infection." (PMID 26067822, 2015).
infection (continued). "Furthermore, increased numbers of CD4+ T cells were apparent in the site of infection of 4x IL-10-/- compared to 4x WT mice (Fig 1Jiversus1Jiv)." (PMID 25974019, 2015). "Direct infection of MDDCs and CD4+ T-cells using this approach was very low and variable." (PMID 25809903, 2015). "Unlike resting CD4+ T cells, activated CD4+T cells are highly susceptible to infection of human immunodeficiency virus 1 (HIV-1)." (PMID 26629815, 2015). "However, we clearly observed a progressive reduction in the numbers of CD3+CD4+ T cells early after the infection, which persists in the two animals with higher viral loads (PB023 and PB028)." (PMID 26640894, 2015). "The TTR-NP mice showed a significant increase in the proportion of CD4+ FoxP3+ T cells among the CD4+ T cells after infection with LCMV-WE or LCMV-Arm compared with the B6 mice in both the spleen and liver, and they remained elevated throughout the chronic infection." (PMID 28210682, 2015). "Furthermore, it has been described that HIV-1 can activate resting T CD4 positive lymphocytes at 3 days post-infection." (PMID 26413773, 2015). "As it is unlikely that sufficient time will have elapsed for parasite antigen-specific CD4+ T cells to have been primed in the lymph node and recruited to the skin site of infection, it was thought possible that these CD4+ T cells were responding to other foreign antigens." (PMID 25974019, 2015). "In contrast to the rapid loss of CD4+ T cells in BLT mice with LAI infection, a largely intact human thymic organ during JRCSF infection could replenish CD4+ T cells in the periphery and slow the net loss of CD4+ T cells." (PMID 26169178, 2015). "Therefore, it is common for HIV-positive patients to be newly diagnosed at various stages of infection, and CD4 counts are used as a surrogate marker for disease progression and immune suppression." (PMID 25908995, 2015). "In addition, an increased number of CD4+CD25+Foxp3+ cells were observed in spleen of mice with EAAI that were in the chronic phase of infection." (PMID 26114122, 2015). "However, the frequencies of Th17 and Treg in CD4+ T cells steadily increased as the infection developed, and significant differences were observed on day 56 PI, compared with the control group (P<0.001)." (PMID 26599407, 2015). "Furthermore, it has been shown that Tregs delay the arrival of effector T cells in the lung during early infection and prevent eradication of tubercle bacilli by suppressing otherwise efficient CD4+ T cell responses." (PMID 26544592, 2015). "Moreover, although absolute CD4 counts are used for assessing the clinical status and eventual progression of the infection in adult patients, populations of lymphocytes including CD4+ are greater in children." (PMID 25622041, 2015). "Non-pathogenic infection of SIV in its natural host African Green Monkeys has also been linked to paucity of CD4+CCR5+ cells." (PMID 26407077, 2015). "We therefore tested whether LPS-matured MDDCs first treated with Env+ pseudovirions could confer efficient infection of autologous CD4+ T-cells." (PMID 25809903, 2015). "Whether increased HIVgag DNA in circulatingPD-1highCTLA-4lowCD127high EI CD4 T cells reflectsincreased infection of a particular follicular CD4 T cell population within the lymphnode needs further investigation." (PMID 26678998, 2015). "CD4+ T cell-derived IL-10 is produced by IL-4+ Th2 cells in the early phase of infection." (PMID 26195548, 2015). "We quantified CD4+ T cell and GC responses 6 days later at 8 days after infection." (PMID 26204259, 2015). "However, the most notable obstacle to infection of resting CD4+ T cells occurs at the stage of reverse transcription." (PMID 26067822, 2015). "It is possible to argue that despite their cytolytic phenotype, V2 specific CD4+ T helper cells induced by the vaccine may be recruited to the site of infection and subsequently become infected and are eliminated, as suggested in HIV infection." (PMID 25665096, 2015).